CASC2 (cancer susceptibility 2)
Diseases named in the same sentence as CASC2 in open-access papers (continued):
Sharing a sentence is not in itself a finding about the gene and the disease.
tumor (69 papers, 2016 to 2025). "Cancer susceptibility candidate 2 (CASC2) acts as a tumor suppressor by targeting miR‐155, restoring suppressors of cytokine signaling 1 (SOCS1) expression and inhibiting HCC proliferation." (PMID 40693828, 2025). "They found that lncRNA cancer susceptibility candidate 2 (CASC2) expression was downregulated in tumor tissues and correlated with poor survival time." (PMID 37205308, 2023). "The LncRNA cancer susceptibility candidate 2 (CASC2) is a novel tumor suppressor with the ability to hamper invasion, migration, and metastasis in HCC cells by suppressing EMT." (PMID 36770654, 2023). "The lncRNA Cancer Susceptibility candidate 2 (CASC2) is located at chromosome 10q26 and was initially identified as a tumor suppressor gene in several types of tumors, including lung, gastric, colorectal, and bladder, among others." (PMID 37469450, 2023). "The lncRNA CASC2 (cancer susceptibility candidate 2) was found to act as a tumour suppressor in Pca through sponging of miR-183-5p, derepressing the miR-183-5p direct target SPRY2 (Sprouty2)." (PMID 35159022, 2022). "LncRNA cancer susceptibility candidate 2 (CASC2) has been reported to serve as a tumor suppressor in carcinogenesis by sponging several miRNAs." (PMID 35928868, 2022). "Sanguinarine has been found to inhibit tumor cell viability and promote apoptosis by inducing the expression of lncRNA cancer susceptibility 2 (CASC2)." (PMID 34458150, 2021). "Compared with that in normal tissues, the expression of CASC2 was significantly decreased in PTC tumors, and the downregulation of CASC2 was significantly associated with tumor size, presence of multifocal lesions, and advanced pathological stage." (PMID 32596158, 2020). "The novel human lncRNA cancer susceptibility candidate 2 (CASC2) has been characterized as a potential tumor suppressor in several tumor types." (PMID 33120918, 2020). "In contrast, cancer susceptibility candidate 2 (CASC2) is a lncRNA with tumor suppressor functionality, acting as a ceRNA for miR-367 and thereby reducing changes in invasive potential/Epithelial-to-mesenchymal transition (EMT) for HCC cells." (PMID 31777593, 2019). "The novel lncRNA gene Cancer Susceptibility Candidate 2 (CASC2) is located on chromosome 10 in humans and has been characterized as a tumor suppressor in human malignancies." (PMID 30857524, 2019). "The lncRNA cancer susceptibility candidate 2 (CASC2), is recurrently deleted in solid tumors, suggesting a tumor suppressor function." (PMID 30926794, 2019). "Downregulation of CASC2 expression was associated with tumor differentiation, lymph node metastasis, and TNM stage, and also predicted a shorter overall time in patients with ESCC." (PMID 31728180, 2019). "LncRNA Cancer Susceptibility Candidate 2 (CASC2) has been demonstrated to act as a tumor suppressor contributing to the development and progression of several cancers." (PMID 31728180, 2019). "Long non-coding RNA cancer susceptibility candidate 2 (lncRNA CASC2) is a tumor suppressor and has been proved to contribute to chemotherapy efficacy." (PMID 35542225, 2018). "LncRNA, cancer susceptibility candidate 2 (CASC2), was found as a tumor suppressor and down-regulated in various cancers." (PMID 30266744, 2018). "The lncRNA cancer susceptibility candidate 2 (CASC2), located on chromosome 10q26, acts as a tumor-suppressor in endometrial cancer." (PMID 28187439, 2017). "Recently, it has been reported that long non-coding RNA (lncRNA) cancer susceptibility candidate 2 (CASC2), a novel tumor suppressor, participates in regulating the carcinogenesis and suppresses tumor progression by sponging microRNAs (miRNAs)." (PMID 28716020, 2017). "Several studies have demonstrated that lncRNA-cancer susceptibility 2 (CASC2) acts as a tumor-suppressive lncRNA in GC, but whether lncRNA-CASC2 can mediate ferroptosis in GC remains unknown, and the specific mechanisms are still largely to be defined." (PMID 38267746, 2024).
tumor (continued). "Regulating the lncRNA cancer susceptibility 2 (CASC2)/miR-18a-5p/retinoblastoma binding protein 8 (RBBP8) axis could also suppress the tumor development." (PMID 37932756, 2023). "Long noncoding RNA cancer susceptibility candidate 2 (CASC2) has been demonstrated as a tumor suppressor by regulating cell proliferation, apoptosis, migration, and chemoresistance in human cancers, including hepatocellular carcinoma, gastric cancer, and prostate cancer." (PMID 33134385, 2020). "CASC2, a well-established tumor suppressive lncRNA, is also associated with cancer resistance." (PMID 29476051, 2018). "However, the potential biological roles and regulatory mechanisms of the novel human lncRNA, CASC2 (cancer susceptibility candidate 2), in tumor biology are poorly understood." (PMID 27198161, 2016). "Various lnRNAs exhibited differential expression in tumor suppressive lncRNAs expression were downregulated such as CASC2, GAS5, MEG3, FER1L4, and LINC00672 expression were in EC tissues in contrast to normal tissues." (PMID 39912983, 2025). "Similar to other tumor suppressor lncRNAs, CASC2 was found to be downregulated in GBM, and its overexpression decreased the malignancy of GBM by cross-talk with miR-21." (PMID 38059120, 2024). "CASC2 is long noncoding RNA identified in chromosome 10 open reading frame 5, it acts as a tumor suppressor." (PMID 38739668, 2024). "The LncRNA CASC2 acts as a tumor suppressor in esophageal squamous cell carcinoma by inhibiting proliferation, migration, and invasion in these cancer cells." (PMID 36770654, 2023). "The expression level of onco-lncRNAs, including PCAT19, MALAT1, and NEAT1, and the tumor suppressor lncRNA, CASC2, was increased and decreased, respectively, in PCa patients compared to the healthy group (P < 0.05)." (PMID 37251950, 2023). "The role of CASC2 as a tumor suppressor has also been established in several cancer types, including thyroid cancer, lung cancer, bladder cancer, osteosarcoma, and oral squamous cell carcinoma by suppressing the proliferation and metastasis." (PMID 36770654, 2023). "Another lncRNA, CASC2, acts as a tumor suppressor in human malignancies, serving as a ceRNA for miR-183 and positively amplifying the expression of another tumor suppressor, SPRY2, a key antagonist of receptor tyrosine kinase signaling." (PMID 38137905, 2023). "Under-expression of CASC2 is correlated with the serous histological subtype, lymph node metastasis, poor histological grade, and large tumor size in ovarian cancer samples." (PMID 36770654, 2023). "Molecular interrelation between CASC2 and Vimentin expression in tumor cells was also evidenced by Tu group." (PMID 33245508, 2022). "LncRNA CASC2 has been reported to be a tumor suppressor in CRC, and its low expression was significantly more frequent in the advanced TNM stage." (PMID 35350786, 2022). "LncRNA cancer susceptibility candidate 2 (CASC2) and protein tyrosine phosphatase gene (PTEN) have been characterized as tumor suppressors and efficient suppressive regulators of cancers." (PMID 34975466, 2021). "In the present study, tumor-suppressive lncRNA cancer susceptibility candidate 2 (CASC2) was downregulated in HCC tissues and cell lines; HCC patients with lower CASC2 expression predicted a shorter overall survival rate." (PMID 35145900, 2021). "In fact, CASC2 performs its tumor suppressor function by interaction with AUF1 to inhibit Bcl-2 mRNA translation and to inhibit CASC2 expression by siRNA, blocking berberine’s anticancer effect." (PMID 33805687, 2021). "Then, the in vitro effects of CASC2 on HCC cell proliferation and apoptosis and the in vivo effects of CASC2 on subcutaneous xenotransplant tumor growth were examined." (PMID 35145900, 2021).
tumor (continued). "On the 25th day, nude mice were sacrificed and the tumor weight was measured; consistently, CASC2 overexpression in Huh-7 or HCCLM3 cells considerably decreased the tumor weight as compared to the lv-NC group; while CASC2 silencing showed the opposite effect." (PMID 35145900, 2021). "Consistently, CASC2 overexpression significantly decreased and CASC2 silencing increased proliferating markers cyclin D1 and ki67 in tumor tissues." (PMID 35145900, 2021). "LncRNA CASC2 is reported to be down-regulated in CC, and acts as a tumor suppressor by inhibiting cell proliferation and migration." (PMID 34703793, 2021). "In vitro, CASC2 overexpression dramatically repressed HCC cell proliferation and inhibited cell apoptosis; in vivo, CASC2 overexpression inhibited subcutaneous xenotransplant tumor growth." (PMID 35145900, 2021). "CASC2, as a tumor suppressor, was subsequently discovered to play a crucial part in multiple tumor diseases, including pancreatic cancer, papillary thyroid cancer, cholangiocarcinoma, glioma, and so on." (PMID 35145900, 2021). "Downregulation of CASC2 reversed the suppression of sanguinarine-induced tumor migration and invasion." (PMID 34458150, 2021). "Compared with the empty and lenti-NC groups, overexpression of CASC2 decreased tumor volumes at each time point." (PMID 33134385, 2020). "The results of qRT-PCR assay revealed that stable transfection of lenti-CASC2 markedly increased the level of CASC2, but decreased miR-155 level in tumor tissues." (PMID 33134385, 2020). "On the other hand, cancer susceptibility 2 (CASC2) functions as a tumor-suppressive factor, and its downregulation has been negatively correlated with tumor grade, and poor patient prognosis and survival." (PMID 32650527, 2020). "Univariate Cox regression model revealed that patients’ clinical characteristics such as age and tumor stage, IDH1 status was associated with their survival as well as CASC2, miR-21, and combined CASC2/miR-21 expression." (PMID 33120918, 2020). "Functional studies in vitro in various cancer cell lines confirmed CASC2 acting as a tumor suppressor as when overexpressed CASC2 was able to inhibit cell proliferation, cell growth, migration and invasion, and to induce apoptosis." (PMID 33120918, 2020). "Recently, it has been reported that lncRNA CASC2 was involved in regulating the carcinogenesis and suppressing tumor progression." (PMID 30857524, 2019). "Our findings suggested that CASC2 functions as a tumor suppressor in ESCC, and its downregulation contributes to ESCC progression." (PMID 31728180, 2019). "In conclusion, our research demonstrated that CASC2 acted as an important tumor suppressor in ESCC progression." (PMID 31728180, 2019). "The novel lncRNA CASC2 is located on chromosome 10 in humans and has been characterized as a tumor suppressor in human malignancies." (PMID 29492259, 2018). "We also assessed the combined effect of CASC2 knockdown and miR-24/221 inhibition of tumor cell apoptosis upon TRAIL treatment." (PMID 29476051, 2018). "The statistical results indicated that CASC2 underexpression was dramatically associated with venous infiltration (P = 0.004), high Edmondson-Steiner grading (P = 0.043) and advanced TNM tumor stage (P = 0.003)." (PMID 28716020, 2017). "RIP and RNA pull-down assays confirmed that the tumor suppressive role of CASC2 is mainly mediated via the down-regulation of miR-21, one potential direct target of CASC2, in a sequence-specific manner." (PMID 28293170, 2017). "We divided the 68 patients with CRC into a high CASC2 tumor expression group (above the mean CASC2 expression, n = 34) and a low expression group (below the mean CASC2 expression, n = 34)." (PMID 27198161, 2016).
tumor (continued). "Lower CASC2 expression was observed more frequently in patients with advanced tumor-node-metastasis stage (III and IV) (P = 0.028)." (PMID 27198161, 2016). "Overexpression of CASC2 is able to inhibit cell proliferation and tumor growth both in vitro and in vivo by extending G0/G1-S phase transition." (PMID 27198161, 2016). "Similarly, CASC2 and LCIIAR showed hypermethylation events that, in various cancers, are linked to aberrant cell proliferation and tumor progression." (PMID 40566344, 2025). "Functionally, these results confirmed that CASC2 could function as a tumor suppressor by acting as a ceRNA to bind to miR-155 and downregulate the expression of SOCS1." (PMID 36816357, 2023). "Their results showed that CASC2 effectively inhibits cell proliferation by modulating the G1‐S checkpoint and inducing cell apoptosis, indicating that CASC2 lncRNA may have a tumor suppressor role." (PMID 37706018, 2023). "Many studies previously demonstrated that CASC2 could function as a tumor suppressor in human cancers." (PMID 36816357, 2023). "Taken together, CASC2 may exhibit its tumor suppressor roles by acting as a competing endogenous RNA to sponge miR-155." (PMID 36816357, 2023). "It was shown that CASC2 promotes the anti-tumor effect of cisplatin in cancer cells." (PMID 36294833, 2022). "Since the protein levels in tumor tissues could be regulated by transcription, mRNA translation, protein stability, or proteasome-mediated degradation, we speculated that CASC2 might upregulate RORA protein expression by maintaining the protein stability." (PMID 34408982, 2021). "CASC2 has been identified as a tumor suppressor that is located on chromosome 10q26." (PMID 33980320, 2021). "The tumor suppressor effects of CASC2 on cancers were well-known previously." (PMID 35145900, 2021). "Moreover, tumor weight was also significantly reduced in the CASC2-expressing group relative to the empty and lenti-NC groups." (PMID 33134385, 2020). "In vivo experiments also indicated that abundance of CASC2 inhibited the growth in 131I-resistant cell-formed tumor, which indicated that CASC2 could act as a therapeutic target for 131I therapy of PTC." (PMID 33134385, 2020). "CASC2 is a well-characterized tumor suppressive lncRNAs in many different types of cancers." (PMID 31931772, 2020). "LncRNA CASC2, as a tumour suppressor, had been discovered in many human tumours." (PMID 32048814, 2020). "Recently, lncRNA CASC2 has been demonstrated to be a tumor suppressor in various types of cancer." (PMID 30675129, 2019). "Conclusively, these results demonstrated that CASC2 could exert as a tumor suppressive lncRNA in ESCC progression via regulating SOCS1." (PMID 31728180, 2019). "Moreover, in-vivo implantation studies using small interfering-CASC2 resulted in increased tumor weight as compared with implantation of pcDNA-CASC2." (PMID 29657304, 2018). "As predicted by miRCode, CASC2 could bind to miR-24 and miR-221 to regulate their expression; next we validated whether CASC2 affected tumor cell TRAIL resistance through acting as a “Sponge” of miR-24 and miR-221." (PMID 29476051, 2018). "Tumor tissues from the remaining 35 enrolled patients (20 radiosensitive patients and 15 radioresistant patients, respectively) were collected to detect the expression of the lncRNAs CASC2, FAM201A, DLEU2, DLX6-AS1, and MCF2L-AS1 by RT-qPCR." (PMID 30574162, 2018). "Here, CASC2 underexpression and miR-367 overexpression were closely correlated with the metastasis-associated clinicopathologic features, such as venous infiltration, high Edmondson-Steiner grading and advanced TNM tumor stage." (PMID 28716020, 2017). "Thus, we concluded that CASC2 functioned as a tumor suppressor by suppressing migration, invasion and EMT progression of HCC cells." (PMID 28716020, 2017). "Accordingly, CASC2 has been identified as a robust tumor suppressor in several cancers." (PMID 28716020, 2017).
tumor (continued). "Taken together, the ability to suppress proliferation indicates that CASC2 may have the potential to act as a tumor suppressor." (PMID 27198161, 2016). "In conclusion, our findings uncovered that CASC2 could act as a tumor suppressor gene and inhibit cell proliferation, migration, and invasion through binding to miR-155, thus increasing the expression of its target gene SOCS1, demonstrating the ceRNA function of CASC2." (PMID 36816357, 2023). "Thus, CASC2 overexpression might repress subcutaneously transplanted tumor growth in mice; while knockdown of CASC2 efficiently facilitated the tumorigenesis ability of HCC cells." (PMID 35145900, 2021). "Moreover, we revealed that CASC2 functioned as a ceRNA of tumor suppressor SOCS1 against miR-155." (PMID 31728180, 2019). "LncRNAs such as GACAT3, DELEC1, CASC2, and LCIIAR exhibited altered methylation status under PFOS exposure, suggesting potential disruption of tumor-suppressive functions or promotion of malignant phenotypes." (PMID 40566344, 2025). "While decreased expression has been seen in CASC2 and PCA3 in cancer, these lncRNAs were down-regulated in G-CIMP-low suggesting their tumor suppressor potential." (PMID 33926464, 2021). "Given the tumor-suppressive role of CASC2 in HCC by our and other groups’ studies, the expression of CASC2 was first validated in collected clinical tissue samples and cell lines." (PMID 35145900, 2021). "In the first pathway, in early-stage CRC, the upregulated CASC2 transmits the signal to HINFP, which is modified by ubiquitination to inhibit tumor growth, and transmits the signal to TF TCF3 through SMG8." (PMID 32211020, 2020). "The results showed that CASC2 knockdown reduced the apoptosis rate of tumor cell; miR-24 or miR-221 inhibition promoted the apoptosis rate; the inhibitory effect of CASC2 knockdown on tumor cell apoptosis could be significantly reversed by miR-24 inhibition or miR-221 inhibition." (PMID 29476051, 2018). "Compared with the lncRNA DLX6-AS1, FAM201A, and CASC2 yielded a superior AUC with specificity and sensitivity for distinguishing radiosensitive ESCC tumor tissues from radioresistant ESCC tumor tissues." (PMID 30574162, 2018). "Therefore, CASC2-mimics may be used in clinical practice to diminish tumor growth and progression." (PMID 29657304, 2018). "Thus, we proposed that CASC2 might be a tumor suppressor in HCC." (PMID 28716020, 2017). "Firstly, real-time PCR was applied to measure CASC2 expression in 75 paired HCC tissues and adjacent non-tumor tissues." (PMID 28716020, 2017). "The results revealed that CASC2 expression in HCC tissues was dramatically decreased, compared with adjacent non-tumor tissues (P < 0.001)." (PMID 28716020, 2017). "Finally, we explored whether high levels of CASC2 could inhibit tumor growth in vivo." (PMID 27198161, 2016). "Major tumor suppressor lncRNAs in GBM are RAMP2-AS1, GAS5 and CASC2." (PMID 38059120, 2024). "We found that overexpression of CASC2 remarkably inhibited the proliferation, migration, and invasion of Huh7 and HepG2 cells, determined by CCK-8 and Transwell experiments, which indicated the tumor suppressor role of CASC2 in HCC." (PMID 36816357, 2023). "Taken together, our findings identified CASC2 as a tumor suppressor to inhibit HCC development by regulating the miR-155/SOCS1 axis, and CASC2 might be a potential therapeutic target of HCC for future clinical treatment." (PMID 36816357, 2023). "Differential expression analysis revealed significant divergence in lncRNA profile between parental tumors and tumor-derived cell cultures in vitro, including the following particles: MALAT1, CASC2, H19, TUSC7, XIST, RP11-838N2.4, DLX6-AS1, GLIDR, MIR210HG, SOX2-OT." (PMID 33245508, 2022). "In vitro, CASC2 overexpression dramatically repressed HCC cell proliferation and inhibited cell apoptosis; in vivo, CASC2 overexpression inhibited subcutaneous xenotransplant tumor growth, confirming the tumor-suppressive role in HCC." (PMID 35145900, 2021).